PAX6 (paired box 6)
Diseases named in the same sentence as PAX6 in open-access papers (continued):
Sharing a sentence is not in itself a finding about the gene and the disease.
congenital nystagmus (4 papers, 2011 to 2024). Nystagmus present at birth or caused by lesions sustained in utero or at the time of birth. "We screened PAX6 mutations in two unrelated patients with congenital nystagmus, and measured DNA-binding affinity through isothermal titration calorimetry (ITC)." (PMID 32080308, 2020). "Of the 16 probands with PAX6 mutations, all had congenital nystagmus and foveal dysplasia." (PMID 21850189, 2011).
ovarian carcinoma (4 papers, 2010 to 2025). A malignant neoplasm originating from the surface ovarian epithelium. "Genes rearranged in ovarian cancer are highly linked to vital genes like MYC, BRCA1, and PAX6 that were also altered in ovarian cancer." (PMID 22811706, 2012). "It was suggested that PAX2 and PAX5 play tumor suppressor roles in ovarian cancer and leukemia, while conversely, PAX3, PAX7, and PAX6 were reported to be oncogenic in embryonal rhabdomyosarcomas and retinoblastoma." (PMID 31235851, 2019).
Retinal coloboma (4 papers, 2007 to 2014). A notch or cleft of the retina or choroid, located vertically below the optic disc. "Analysis of PAX2, a cause of optic disc and retinal coloboma (OMIM 120330), has identified roles in both patterning the optic stalk/neural retina boundary together with PAX6 (i), and for fissure closure and correct development of the optic disc (v and vi)." (PMID 24412933, 2014). "Moreover, another mouse study suggested that tissue-specific over-expression of Rybp (a zinc finger protein) in the lens could reduce CRYBA4 gene expression while heterozygous Rybp null mice often resulted in retinal coloboma characterized by expanding localization of PAX6." (PMID 22792142, 2012).
teratoma (4 papers, 2012 to 2020). A non-seminomatous germ cell tumor characterized by the presence of various tissues which correspond to the different germinal layers (endoderm, mesoderm, and ectoderm). "The pigmented cells appeared as a component of PAX6 positive optic vesicle-like structures within the teratoma and formed a distinct polarised PMEL17 positive monolayer, with basal DAPI positive nuclei and apical pigmentation similar to RPE." (PMID 27653836, 2016). "To confirm the findings on PAX6 and SOX1, we performed immunostaining on cryostat sections from the teratomas." (PMID 32587369, 2020). "The transcriptional analysis of teratoma tissues also showed the expression of genes of all three germ layers: the endoderm (SOX7, and SOX17), mesoderm (BRACHYURY, and MIXL1), and ectoderm (PAX6, and TUJ1)." (PMID 31888235, 2019). "We did find that the expression of Pax6 and Sox17 (except in GATA6) was lower than ES-EB, even though all of the selected iPSC lines in our study can generate teratoma, a gold standard of pluripotency." (PMID 22529890, 2012).
thyroid cancer (4 papers, 2010 to 2025). "PAX6 showed the most interactions in the largest network, and has been reported to be a cancer driver in various cancers including lung breast, colon, liver, pancreatic, and thyroid cancers." (PMID 34989314, 2022).
Waardenburg syndrome (4 papers, 2022 to 2026). A disorder characterized by varying degrees of deafness and minor defects in structures arising from neural crest, including pigmentation anomalies of eyes, hair, and skin. "In the 1990s, it became evident that DDs are often caused by HI of TF genes, such as aniridia caused by PAX6 HI or Waardenburg syndrome caused by PAX3 HI." (PMID 35089335, 2022).
brain malformations (3 papers, 2009 to 2021). "Correlation between phenotype and genotype of PAX6 mutations is still in its infancy in regard to brain malformations." (PMID 19862335, 2009). "In addition, PAX6 gene mutations can be associated with brain malformations." (PMID 23799907, 2013). "Brain malformations have also been shown due to inhibition of Pax-6, which is necessary for the closure of the nascent neural tube, as well as CB1-mediated ocular malformation, lack of memory retention and hyperactivity, and inhibition of new synapses formation in hippocampal neurons." (PMID 34068903, 2021).
depression (3 papers, 2022 to 2024). "The disruption of Pax6 has also been linked to major depressive disorder." (PMID 39857659, 2024). "An overlap of these genes with risk genes from major depressive disorder genome‐wide association studies revealed the involvement of the master regulators TCF4 and PAX6 in emotion and reward processing." (PMID 35796185, 2022). "The identification of regulatory genes TCF4 and PAX6 thereby implies a potential role of master regulators for functional brain imaging in major depression." (PMID 35796185, 2022). "In animal models of depression, naringenin treatment has been shown to upregulate BDNF, SHH, GLI1, NK2 Homeobox 2 (NKX2.2), and Paired box protein Pax-6 (PAX6)." (PMID 39478958, 2024). "In line with core symptoms of depression, TCF4 affected subordinate genes positively and negatively correlated with emotional face recognition and PAX6 mainly affected those genes that were negatively correlated with reward processing." (PMID 35796185, 2022).
Hydrocephalus (3 papers, 2008 to 2022). Hydrocephalus is an active distension of the ventricular system of the brain resulting from inadequate passage of CSF from its point of production within the cerebral ventricles to its point of absorption into the systemic circulation. "Unlike the previous report, we have not detected hydrocephalus in our Nfix-/- mice, but instead find unusual Pax6- and DCX-positive cells within the lateral ventricles of the mice." (PMID 18477394, 2008).
infiltrating ductal carcinomas (3 papers, 2015 to 2025). "The percentage of Pax6 promoter methylation was about 50% within the infiltrating ductal carcinomas cohorts, even if not always associated with a reduction in RNA expression." (PMID 40506992, 2025). "However, clinical investigation of infiltrating ductal carcinomas found a higher PAX6 protein expression in biopsies from ER-negative cases compared with ER-positive ones." (PMID 40506992, 2025). "They observed frequent promoter hypermethylation of BRCA2, CDH13, MSH6, PAX5, PAX6, and WT1 genes in both DCIS and adjacent invasive ductal adenocarcinoma lesions." (PMID 40131297, 2025).
ocular albinism (3 papers, 2012 to 2020). Albinism affecting the eye in which pigment of the hair and skin is normal or only slightly diluted. "Most families had a suspected diagnosis of PAX6-related phenotype (6/11 patients), ocular albinism (3/11 patients) or idiopathic IN (1/11 patients)." (PMID 32744312, 2020). "Based on our initial clinical examination, most common provisional diagnoses were PAX6-related phenotype and ocular albinism." (PMID 32744312, 2020). "Ninety percent of our cases were initially misdiagnosed as PAX6-related phenotype or ocular albinism prior to NGS." (PMID 32744312, 2020).
pancreatic adenocarcinoma (3 papers, 2014 to 2018). "When PAX6 was knocked down by stably transfected PAX6 shRNA in pancreatic adenocarcinoma HPAFII cells, a 4-fold decrease in Dkk3/REIC gene expression was observed." (PMID 25029272, 2014).
pterygium (3 papers, 2014 to 2025). A wedge-shaped fibrovascular lesion arising from the bulbar conjunctiva and extending to the cornea. "Downregulation of Pax6 is associated with abnormal epidermal differentiation in severe ocular surface diseases such as chemical burn, Stevens-Johnson syndrome, and other diseases as pinguecula and pterygium (unpublished observation)." (PMID 24498087, 2014). "The most important result of the current study is a decreased PAX6 mRNA expression in EBMD, SND, and pterygium conjunctival IC samples and a decreased PAX6 protein expression in EBMD, SND, and pterygium corneal epithelial cells." (PMID 40094891, 2025). "In corneal epithelial samples, PAX6 protein, DSG1 mRNA and protein, miRNA-138-5p, and miR-204-5p expression were significantly lower in EBMD, SND, and pterygium samples than in controls (p ≤ 0.02)." (PMID 40094891, 2025). "In the corneal epithelium, we found a decreased PAX6 protein expression and decreased DSG1 mRNA and protein expression in EBMD, SND, and pterygium samples." (PMID 40094891, 2025). "However, PAX6 protein expression was significantly lower in samples from EBMD, SND, and pterygium patients compared to controls (p < 0.0001 for all)." (PMID 40094891, 2025). "Interestingly, our measurement results in EBMD, SND, and pterygium in central corneal epithelial cells show similarities with limbal epithelial cells in AAK, particularly PAX6 and DSG1 mRNA and protein expression." (PMID 40094891, 2025). "PAX6, DSG1, miR-138-5p, and miR-204-5p expression is decreased in the corneal epithelium of epithelial basal membrane dystrophy, Salzmann nodular degeneration, and pterygium subjects." (PMID 40094891, 2025). "In addition, interestingly, there was an increased FABP5 mRNA expression without an increased FABP5 protein expression, parallel to a decreased PAX6 and DSG1 expression in conjunctival IC samples and in corneal epithelium of pterygium patients." (PMID 40094891, 2025). "In our study, we found no change in expression of PAX6 in pterygium or pinguecula, consistent with the relative lack of keratinization." (PMID 34769520, 2021).
retinopathy of prematurity (3 papers, 2020 to 2023). A bilateral retinopathy characterized by neovascularization, scarring, retinal detachment, and eventually blindness. "This particular appearance of the fovea can be associated with conditions such as albinism, PAX6 mutation, aniridia, retinopathy of prematurity (ROP), SLC38A8 mutations, optic nerve hypoplasia, achromatopsia, and cone-rod dystrophy, but can also be found in normal children." (PMID 36836571, 2023).
Stevens-Johnson syndrome (3 papers, 2013 to 2021). Stevens-Johnson syndrome is a limited form of toxic epidermal necrolysis characterized by destruction and detachment of the skin epithelium and mucous membranes involving less than 10% of the body surface area. "Expression of transcription factor PAX6 was significantly downregulated in corneal epithelial cells isolated from the severe ocular surface inflammatory diseases of Stevens-Johnson Syndrome and recurrent pterygium, and from Sjögren’s syndrome." (PMID 34769520, 2021).
Stickler syndrome (3 papers, 2021 to 2025). Stickler syndrome is an inherited vitreoretinopathy characterized by the association of ocular signs with more or less complete forms of Pierre-Robin sequence, bone disorders, and sensorineural deafness (10% of cases). "Exome sequencing identified 21 potential pathogenic variants of 13 genes in 20 of 75 (26.7%) probands, including genes for Stickler syndrome (COL11A1 and COL2A1; 6/20), FEVR (FZD4, LRP5, and TSPAN12; 5/20), and others (FBN1, GPR179, ZEB2, PAX6, GPR143, OPN1LW, FRMD7, and CACNA1F; 9/20)." (PMID 38243264, 2024).
Stroke (3 papers, 2018 to 2025). Sudden impairment of blood flow to a part of the brain due to occlusion or rupture of an artery to the brain. "This study provides the first evidence that miR‐365, upregulated in the ischemic brain, inhibits the stroke‐induced conversion of reactive astrocytes into neurons via inhibition of PAX6 expression by targeting the 3′‐UTR of Pax6, and exacerbates ischemic brain injury." (PMID 29451327, 2018). "Neurosphere cells expressed Paired Box 6 (Pax6, a transcription factor implicated in the regulation of neurogenesis) and GFP, indicating that this vast network of neuronal precursors was limited to and expanded throughout the stroke area and that none had originated in the SVZ." (PMID 33132848, 2020).
astrocytoma (2 papers, 2010). "Subsequent to GLI1 silencing, we observed an increase in PAX6 expression in the transfected astrocytoma cell line U87MG." (PMID 21059263, 2010). "On the contrary, we observed significant correlation of GLI1 expression with downstream target genes PTCH1 (p = 0.07), Cyclin D2 (p = 0.006), Plakoglobin (p = 0.02), PAX6 (p = 0.006) and NKX.2.2 (p = 0.0001) in astrocytoma cell lines." (PMID 21059263, 2010).
bladder cancer (2 papers, 2014 to 2023). "Taken together, PAX6 methylation status is able to distinguish bladder cancer patients who are most likely to have a high risk of recurrence." (PMID 37627900, 2023). "Hence, PAX6 methylation has diagnostic implications for bladder cancer." (PMID 37627900, 2023). "T1G3 bladder cancer patients who treated with Bacillus Calmette–Guerin (BCG) immunotherapy had a higher recurrence rate when the tumors harbored PAX6 methylation as compared to those that were unmethylated." (PMID 37627900, 2023). "The methylation rate of the PAX6 promoter was found to be significantly higher in bladder cancer tissues as compared to adjacent normal tissues." (PMID 37627900, 2023). "Methylation of PAX6-promoters is increased in early bladder cancer and methylated PAX6-promoters could be a represent biomarker for this disease." (PMID 24454925, 2014). "In high-grade pT1 tumors, the methylation profile of PAX6, ATM, CHTR, and RB1 independently predicted the recurrence of bladder cancer." (PMID 37627900, 2023).
brain ischemia (2 papers, 2016 to 2018). Diminished or absent blood supply to the brain caused by obstruction (thrombosis or embolism) of an artery resulting in neurologic damage. "Cerebral ischemia increased miR‐365 levels in the brain, and miR‐365 repressed PAX6 expression in the astrocytes." (PMID 29451327, 2018).
breast tumor (2 papers, 2017 to 2025). "Methylation on the CpG site in PAX6 gene endured a significant reduction during the progression from primary breast tumor to lymph node metastasis." (PMID 40506992, 2025). "Nonetheless, PAX6 expression was found to be significantly increased in primary breast tumors compared to normal breast tissues." (PMID 40506992, 2025). "Meanwhile, discrete groups of tumor cells isolated from three regions of one breast tumor (case 3) probably shared the origin-specific duplication of the PAX6 gene." (PMID 28977854, 2017).
colon cancer (2 papers, 2017 to 2020). "In contrast, P2-driven HNF4A is induced in colon cancer though combined actions of Paired Box 6 (PAX6) and HNF1A." (PMID 32998360, 2020).
congenital glaucoma (2 papers, 2016 to 2019). "However, none of the nine individuals with PAX6 mutations had congenital glaucoma." (PMID 27124303, 2016).
Congenital ptosis (2 papers, 2013). Congenital ptosis is characterized by superior eyelid drop present at birth. "Mutations in the PAX6 have not yet been reported to be associated with congenital fibrosis of extraocular muscle, but may be associated with congenital ptosis." (PMID 23799907, 2013).
cyst (2 papers, 2013 to 2023). A sac-like closed membranous structure that may be empty or contain fluid or amorphous material. "To quantitatively assess the efficiency of retinal induction within our cyst cultures, we immunostained the cysts for the optic vesicle stage-related markers PAX6, RX, OTX2 and the optic cup stage-related marker CHX10." (PMID 23358448, 2013). "These cryosectioned cysts showed strong signals for PAX6 and RX, especially apically, suggesting that the stronger basal signal in the whole-mount immunofluorescence of large cysts might be due to the hindered penetrance of the antibodies into the center of the cyst." (PMID 23358448, 2013).
dry eye (2 papers, 2006 to 2026). "It is not clear whether the keratopathy is a direct result of reduced PAX6 gene dosage in the cornea itself, or due to recurrent corneal trauma secondary to defects such as dry eye caused by loss of PAX6 in other tissues." (PMID 16914058, 2006).
ectopia lentis (2 papers, 2021 to 2023). "In this manuscript, we describe a novel PAX6 variant in a Chinese patient who was first diagnosed with retinal detachment and ectopia lentis, to broaden the genetic variant spectrum of this rare condition." (PMID 37542296, 2023).
hamartoma (2 papers, 2018 to 2025). A benign and excessive tumor-like growth of mature cells and normal tissues which grow in a disorganized pattern. "Thus, for the remainder of this study, we focused on the peripheral retina where the Pax6-Cre allele was most active, avoiding the central retina, which was readily distinguishable as it forms a visible hamartoma comprised of remaining wild-type cells in Pten-cKO retinas." (PMID 40526494, 2025). "The spatial specificity of the hamartoma-like lesions coincided with the previously reported dorsal-central gap in Pax6::Cre driver activity." (PMID 29716894, 2018). "These lesions resembled the hamartomas characteristic of PHTS, and hereafter are referred to as hamartoma-like, whereas no such masses were detected in P21 wild-type animals or in animals heterozygous for a Pten mutation (Ptenfl/+;Pax6::Cre+; data not shown)." (PMID 29716894, 2018).
Hypoglycemia (2 papers, 2021 to 2024). A decreased concentration of glucose in the blood. "Changes in maternal PDX1 methylation, NGN3 and Pax6 expression levels may lead to abnormal glucose metabolism in neonates, which has a close bearing on neonatal hypoglycemia and blood glucose levels caused by GDM." (PMID 38356808, 2024). "The results of this study suggest that neonatal hypoglycemia may be related to the decreased expression levels of PDX1, NGN3 and Pax6 genes in pregnant women with GDM." (PMID 38356808, 2024).
insulinoma (2 papers, 2010 to 2018). "We show that miR-7 and miR-375 target specific sites within the Pax6 3′ UTR in a mouse pancreatic β-insulinoma cell line." (PMID 30290306, 2018). "We first showed by miRNA overexpression, miR-7 and miR-375 reporters, Pax6 3′ UTR reporters, and Tud inhibitors of miR-7 and miR-375, that miR-7 and miR-375 regulate PAX6 protein levels within the β-TC-6 insulinoma cell line." (PMID 30290306, 2018). "Wild type Pax6 and the transcription factor with a deletion of exon 6 were transiently transfected into INS-1E insulinoma cells serving as a model system for pancreatic endocrine cells." (PMID 20377917, 2010).
ischemia (2 papers, 2018 to 2020). A hypoperfusion of the BLOOD through an organ or tissue caused by a PATHOLOGIC CONSTRICTION or obstruction of its BLOOD VESSELS, or an absence of BLOOD CIRCULATION. "We mainly found that miR‐365 inhibited ischemia‐induced astrocyte‐to‐neuron conversion by targeting Pax6 and knockdown of miR‐365 enhanced the PAX6‐mediated astrocytes‐derived neurogenesis in the rat brain after ischemic injury." (PMID 29451327, 2018). "PAX6 is a pro‐neurogenic transcription factor and highly expresses in reactive astrocytes following ischemia, and it plays a key role in the conversion of astrocytes into neurons." (PMID 29451327, 2018). "Then, we injected a mixture of the Lv‐GFAP‐EGFP and Lv‐Pax6 or Lv‐mCherry into the ipsilateral striatum of rats 7 days before MCAO and sacrificed the rats 14 days after the induction of ischemia to assess the effects of exogenous PAX6 on ischemia‐induced astrocyte‐to‐neuron conversion." (PMID 29451327, 2018).
keratoconus (2 papers, 2022). A degenerative, structural disorder of the eye, characterized by a cone-shaped protrusion of the cornea. "Keratoconus is a type of corneal ectasia and could potentially occur in AS patients due to genetic factors such as a mutation in the PAX6 gene." (PMID 36119140, 2022).
periodontitis (2 papers, 2023 to 2024). An acute or chronic inflammatory process that affects the tissues that surround and support the teeth. "Importantly, our analysis revealed the loss of PAX6 and its regulatory interactions during periodontitis." (PMID 37834287, 2023). "Beyond its role in periodontitis, IL-6 induces oral carcinogenesis by promoting the hypermethylation of tumor suppressor genes, such as CHFR, GATA5, and PAX6." (PMID 38612423, 2024). "Another member of Module 3, also regulated by PAX6, is CRYBB1, a gene that is over-expressed in periodontitis." (PMID 37834287, 2023).